EGFR (epidermal growth factor receptor)
Diseases named in the same sentence as EGFR in open-access papers (continued):
Sharing a sentence is not in itself a finding about the gene and the disease.
cancer (continued). "EGFR-TKI-induced dry skin not only causes a decrease in patient quality of life, but also influences the continuation of cancer treatment." (PMID 32260143, 2020). "EGFR path is one of the major oncogenic pathways via Ras/Raf/MEK/ERK signaling to promote the cancer cell proliferation, migration, and invasion." (PMID 33194732, 2020). "Since EGFR expression is regulated by multiple factors, including specific protein (Sp) transcioption factors through interaction with HDAC1 and HDCA2 in cancer cells 19, 20, we tested the effect of Sp1 and Sp3 knockdown on EGFR activity and HDCA expressions." (PMID 32226300, 2020). "Such interactions promoted EGFR mRNA translation leading to cell proliferation, survival, and invasion of cancers." (PMID 32900991, 2020). "The mechanisms of cancer expansion via EVs are various and include immunosuppression, metabolic reprogramming, and the transfer of active oncogenes, e.g., EGFR, the mutant form of KRAS, and integrins into the cells of the target organ." (PMID 32916986, 2020). "In this section, we observe evidence that this is actually the case, highlighting the cancer histotypes in which it occurs, the processes unleashed and the EGFR signalling partners involved." (PMID 33302515, 2020). "In-vitro studies have demonstrated that targeting cholesterol synthesis results in sensitizing resistant cancer cells to EGFR inhibitors." (PMID 32594310, 2020). "Studies have shown that ncRNAs, along with EGFR and cellular ROS, display crucial roles in the progression of cancer." (PMID 35006436, 2020). "We identified 254 differently expressed genes (DEGs) in EGFR-mutant cancers in the GSE32863 dataset." (PMID 32277151, 2020). "We will examine the prospects of utilizing EVs positive for EGFR as liquid biopsies in cancer, and finally, we explore recent developments in bio-engineering EVs with EGFR targeting abilities." (PMID 33143170, 2020). "Our results of the regulatory role of UCH-L1 in EGFR stability will help further understand the functions of this deubiquitinating enzyme in cancer development, progression and treatment." (PMID 32042339, 2020). "This new combinatorial therapy includes drugs that are approved for use in cancer treatment, like anti‐EGFR therapies, or that are currently in clinical trials, like PI3Kβ inhibitors, making these findings easier to translate in the clinical practice." (PMID 32672423, 2020). "When cancer cells are irradiated and undergo cell-cycle arrest, EGFR contributes to successful repair, allowing cells to exit the arrested phase." (PMID 32157215, 2020). "Overexpression and oncogenic role of epidermal growth factor receptor (EGFR) in malignant tumors are commonly identified." (PMID 33489872, 2020). "Epidermal growth factor receptor (EGFR) is a central molecule of cancer cell proliferation as well as invasion and metastasis." (PMID 32521759, 2020). "Several researches have been reported that EGFR signal pathway exerts disruption of desmosomes and adherens junctions leading to dissociation of cancer cells and improved cell migration, invasion, anoikis resistance, and stem cell-like properties." (PMID 32376896, 2020). "Specifically, EGFR is a widely studied oncogene with a potential role in cancer therapeutics, six are core genes (AURKA, CDK1, CDT1, PRKDC, RAD51, and XRCC2), six are potential drug targets, and five were identified as drug actionable genes." (PMID 33240468, 2020). "Epidermal growth factor receptor (EGFR) is over-expressed in many cancer cells and is a good target for cancer therapy." (PMID 33023595, 2020). "CTX is a chimeric monoclonal antibody that binds to EGFR and inhibits EGFR tyrosine kinase activity, which in turn suppresses EGFR-positive cancer development." (PMID 32170176, 2020). "Inhibition of CDK4/6 in combination with anti-EGFR therapy has been a recent approach used in cancer therapeutics, including the treatment of HNSCC." (PMID 33302499, 2020).
cancer (continued). "To expand our knowledge in this area, we are interested in searching for new and previously uncharacterized component(s) of the mTOR signaling network in advanced EGFR-mut cancers." (PMID 32923403, 2020). "In contrast, combinations of several markers have proved to be of superior diagnostic value, such as the combination of EMMPRIN/EpCAM/MUC1/EGFR, which reliably separated cancer patients from healthy controls with a high AUC value of 0.85." (PMID 32731639, 2020). "Epidermal growth factor receptor (EGFR) signaling is one of the most intensely studied determinants of epithelial cell proliferation and is persistently activated in various human cancers, including cSCC." (PMID 33294587, 2020). "The EGFR inhibitor also completely blocked CM-induced invasion of cancer cells from the spheroids into the matrix." (PMID 32731484, 2020). "Here we take CPV as the model of parvoviruses to explore the mechanism driving CPV-induced cell cycle arrest with a focus on EGFR-mediated signaling to aid in parvovirus-mediated virotherapies for cancer control." (PMID 32877289, 2020). "The same group showed TUFM-NLRX1 interaction also in cancer cells, in which NLRX1 promoted cetuximab, an epidermal growth factor receptor (EGFR) inhibitor, -induced autophagy and mediated resistance to cancer treatment." (PMID 33344269, 2020). "It was also observed that blocking both Akt and EGFR leads to cell death, which can be studied further to check its specificity to cancer cells." (PMID 32731484, 2020). "In hepatocellular carcinoma, YTHDF2 suppresses the mitogen-activated protein kinase 1 (ERK)/mitogen-activated protein kinase 7 (MEK) signaling pathway by reducing EGFR expression and subsequently inhibits cancer cell proliferation and growth." (PMID 32709063, 2020). "Dysregulated of the epidermal growth factor receptor (EGFR) is an oncogenic driver of many human cancers, promoting aberrant cell proliferation, migration, and survival." (PMID 32050662, 2020). "Increased EGFR expression has been found in multiple types of human cancers, including lung, breast, colon, oral and kidney cancers." (PMID 32337844, 2020). "The anti-EGFR pro-apoptotic CL4 is an aptamer raised against the epidermal growth factor receptor (EGFR) and found to have a strong cytotoxic effect in EGFR positive cancer cells." (PMID 32957732, 2020). "Inhibition of cholesterol upregulation helped cancer cells overcome the development of EGFR tolerance and then induced apoptosis." (PMID 33113804, 2020). "Gefitinib (EGFR inhibitor) reduces cancer cell multiplication and enhances the cytotoxicities of carboplatin and docetaxel." (PMID 32245065, 2020). "It seemed that, such treatment indicated a novel approach for future studies concerning the anti-cancer biomarkers, including the anti-EGFR treatment." (PMID 33243184, 2020). "Cancers with mutation of RAS and BRAF genes were found to be resistant to anti-EGFR (epidermal growth factor receptor) therapy." (PMID 32867793, 2020). "During this process the cancer cells gain TFs in the neuroendocrine pathway that contribute to AR-independent (prostate) or EGFR-independent (lung) growth and survival because it imparts tumors with a stem cell-like state." (PMID 33297508, 2020). "Standard chemotherapy reduces the replication of cancer cells, but EGFR inhibitors are capable of cancer proliferation and survival." (PMID 32992587, 2020). "HER2 aptamers have also been used to deliver EGFR (epidermal growth factor receptor) siRNAs into HER2-positive cancer cells." (PMID 32316469, 2020).
cancer (continued). "Anti-EGFR mAbs and small molecule tyrosine kinase inhibitors (TKIs) targeting EGFR were approved by FDA for cancer therapy." (PMID 33023595, 2020). "Recently, activation of transducer and activator of transcription 3 (STAT3) in NSCLC appeared as an alternative resistance mechanism allowing cancer cells to elude the EGFR signaling." (PMID 32438613, 2020). "MDM2/4 as well as EGFR amplifications, have recently been described in association with hyperprogression on ICI in diverse cancers." (PMID 32110946, 2020). "Activation of the epidermal growth factor receptor (EGFR) is a vital oncogenic signaling regulator for the invasion and metastasis of cancer cells." (PMID 33613617, 2020). "The same research group applied a similar strategy for imaging of cancer cells by targeting the overexpression of a transmembrane protein called epidermal growth factor receptor (EGFR) which is commonly found in many cancer cells." (PMID 32455561, 2020). "Previous research results indicate that RAS is a key downstream effector of epidermal growth factor receptor (EGFR), which is activated by mutation and/or overexpression in a variety of human cancers." (PMID 33299862, 2020). "EGFR drives tumorigenesis by multiple down-stream signaling pathways thereby stimulating cancer cell proliferation, survival and chemoresistance." (PMID 33643898, 2020). "CC cells that are resistant to the EGFR inhibitor erlotinib acquire cancer stem cell (CSC) properties via activation of IGF2/IR/IGF-1R and its downstream signaling to induce EMT." (PMID 32708604, 2020). "ET-1 acts as a direct survival and proliferation factor for cancer cells and is involved in the transactivation of other receptors, including the epidermal growth factor receptor (EGFR)." (PMID 32197449, 2020). "Gefitinib is an EGFR inhibitor and is the first approved molecular targeted therapy for cancer treatment in Japan." (PMID 32833992, 2020). "The high expression of EGFR in many cancer cells makes those cell types strong candidates for treatment with monoclonal antibodies and ADCs directed against EGFR." (PMID 31969631, 2020). "The anti-EGFR-PG-Doxo resulted in a tenfold increase of uptake into EGFR-positive cancer cells compared with untargeted PG-Doxo." (PMID 32854720, 2020). "Overexpression or activation of epidermal growth factor receptor (EGFR) occurs commonly in multiple human cancers and promotes tumorigenesis." (PMID 33643898, 2020). "We used A431 cells, an EGFR-overexpressing cancer cell line, to investigate the change in TiO2 PEG NP cellular uptake after EGF conjugation." (PMID 33003324, 2020). "Epidermal growth factor receptor activation is a vital regulator of oncogenic signaling in cancer cell invasion and metastasis." (PMID 32719793, 2020). "A number of E3 ubiquitin ligases apart from Cbl have also been shown to regulate expression of mutant EGFR in various cancer types, some of which target EGFR for degradation by the proteasome." (PMID 33302515, 2020). "Overexpression of TGFα and EGFR is also detected in a variety of human cancers, including epithelial and lung cancers, and gliomas." (PMID 32432044, 2020). "We next examined the response of the cells to EGFR-TKIs (gefitinib and afatinib) and conventional anti-cancer drugs (cisplatin and taxol), which are standard treatment options in NSCLC." (PMID 32130260, 2020). "All these PROTACs can efficiently eliminate EGFR at low-nanomolar concentrations, and exerted sustained inhibitory effects on cancer cell proliferation and downstream kinases signaling of EGFR." (PMID 32983997, 2020). "Trifluoperazine, an existing phenothiazine-like antipsychotic drug, was repurposed as a potential anti- cancer stem-like cell agent by overcoming epidermal growth factor receptor-tyrosine kinase inhibitor and chemotherapy resistance." (PMID 31949488, 2020).
cancer (continued). "Kinases are the driving force of phosphorylation cascades, and kinase dysfunction/dysregulation has been associated with oncogenesis, as for instance demonstrated for the Epidermal Growth Factor Receptor (EGFR) in various cancers." (PMID 32576205, 2020). "Among various types of EGFR inhibiting agents, small molecule tyrosine kinase inhibitor is established clinical activity and regulatory approval for the treatment of cancer." (PMID 33224225, 2020). "The benefits of multiple growth factor inhibition is not limited to EGFR TKIs, and D3 combination with other cancer drugs results in decreased persister frequency in nine out of eleven cancer cell lines tested." (PMID 32066763, 2020). "EGFR is a key regulator of complex signaling cascades related to cancer cell growth, signaling, differentiation, adhesion, migration, and survival." (PMID 33158043, 2020). "Accumulating studies have demonstrated that acquired resistance to chemotherapeutic agents such as platinum, EGFR-TK inhibitors, and ALK inhibitors is associated with increased PD-L1 in cancer cells." (PMID 32024543, 2020). "For this reason, the EGFR is a target molecule for inhibiting cancer cell growth, and various EGFR tyrosine kinase inhibitors (EGFR-TKIs) have been developed for proactive use against refractory cancers." (PMID 32260143, 2020). "Several molecules, of which the lead molecule was 23, were highly potent in a set of cancer cell lines and presented nanomolar potency against EGFR in biochemical assays." (PMID 33479617, 2020). "To identify additional potential mechanisms of treatment escape in response to EGFR-TKIs, we therefore investigated regulation of genes causally linked to cancer according to the COSMIC Cancer Gene Census effort." (PMID 32234966, 2020). "The efficacy of apoptosis detection using the novel AV-SNAP-BG-647 fusion proteins was assessed on adherent EGFR-overexpressing cancer cell lines treated with an EGFR-specific ADC, as well as on suspension cells (Jurkat cells) after heat shock treatment." (PMID 33270761, 2020). "The EGFR/HER2 signaling network is pivotal in controlling cancer proliferation and metastasis through the downstream effectors of AKT, ERK, and STAT3." (PMID 32143669, 2020). "EGFR is highly expressed in many cancers such as nonsmall cell lung cancer (NSCLC), breast, colorectal, prostate, gliomas, and bladder cancer." (PMID 33273921, 2020). "Members of the human epidermal growth factor receptor (EGFR/HER) family, which also includes, in addition to EGFR, HER2, HER3, and HER4, have been found overexpressed or mutated in several types of cancer." (PMID 32847130, 2020). "In traditional anti-cancer therapy, epidermal growth factor receptor (EGFR)-tyrosine kinase inhibitors (TKI) have been proven to be beneficial for patients with EGFR mutations." (PMID 33276757, 2020). "Using first-line drugs cisplatin (CDDP) and Cetuximab in control groups, the anti-cancer effect of the new gene therapy strategy which combines EGFR-inhibition and apoptosis-inducing was investigated on EGFR-overexpressing cancer cell HEP-2." (PMID 32745124, 2020). "The overexpression of EGFR has been reported in many cancers including NSCLC, which leads to cell proliferation and anti-apoptosis." (PMID 31935933, 2020). "Currently, only one epidermal growth factor receptor (EGFR)-specific targeted-immunotherapy with cetuximab antibody is available for the management of this cancer." (PMID 32547936, 2020). "Overexpression of the EGFR oncogene has been identified in many cancers that are a product of aberrant EGFR signaling." (PMID 33437516, 2020). "The overexpression of epidermal growth factor receptor (EGFR) in a high number of GACs pointed at this protein as a promising target in this type of cancer." (PMID 32751679, 2020). "The continuous production of neutrophil elastase by TINs maintains the EGFR activity of cancer through PAR2 stimulation." (PMID 32121107, 2020).
cancer (continued). "Increased expression of neuroendocrine markers and decreased EGFR expression were detected in TKI resistant SCLC transformed cancers compared with resistant NSCLCs." (PMID 35582610, 2020). "CAFs are also known to confer resistance to anti-EGFR therapies among different cancer types including colon, lung, breast, and in HNC." (PMID 32028632, 2020). "We analyzed a publicly available cancer cohort (n = 9052) from cBioPortal to identify alteration frequencies for EGFR, PIK3CA, and PTEN genes across all breast cancer subtypes." (PMID 33148288, 2020). "The TR-PINs exhibited up to a 24-fold improvement in cancer cell binding compared with EGFR-specific cetuximab-targeted PINs (Cet-PINs) in low-EGFR-expressing cell lines." (PMID 32726945, 2020). "Quercetin is an efficient anti-cancer agent as evidenced by an EGFR decrease in EGFR-overexpressing HNSCC." (PMID 32486484, 2020). "For example, suppression of EGFR signaling with therapeutic anti-EGFR mAbs or inhibitors is used in cancer therapy, but EGFR also plays a central role in skin homeostasis and cardiovascular cell survival." (PMID 33209247, 2020). "The promotion of cancer metastasis by MMP‐9 through EGFR‐mediated signaling pathway has been addressed." (PMID 32180962, 2020). "Similarly, KRAS mutation status may affect susceptibility of EGFR overexpressing cancers to ADCC." (PMID 32698317, 2020). "To establish the clinical relevance of our findings, we took advantage of publicly available cancer patient databases and analyzed the mRNA expression levels of USP25 and how they are linked to EGFR." (PMID 33202887, 2020). "The onco-suppressor upstream factors are able to inhibit cancer malignancy via the inhibition of EGFR." (PMID 32380783, 2020). "In fact, in many cancer models, the removal of c-Myc, H-Ras, K-Ras, EGFR, mutant BRAF, c-Kit, or Met leads to growth arrest, differentiation, and apoptosis." (PMID 32528950, 2020). "Another study demonstrated that REG4-induced EGFR/Akt pathway activation promotes cancer cell progression directly and polarization of macrophages to M2 phenotype." (PMID 33489872, 2020). "Another important goal is the targeting of cancer-specific antigens using a cancer-specific mAb (CasMab) because EGFR, HER2, PODXL, and CD44 are widely expressed in normal tissues." (PMID 33000243, 2020). "In this study, the pathway analysis showed that the potential targets such as VEGFA and EGFR were mainly enriched in pathways including proteoglycans in cancer and estrogen-signaling pathway." (PMID 32256653, 2020). "The ability of ADCs to deliver highly potent payloads in the targeted cancer cell (e.g., with EGFR expression) with reduced off-target toxicity makes this approach very attractive in the management of MM." (PMID 33023139, 2020). "EGFR signaling is aberrantly activated in a number of cancers, including lung, head and neck, colon, brain, and pancreas, due to activating mutations, amplifications, or increased protein levels." (PMID 33287140, 2020). "CAFs share a common environmental niche with cancer cells and collectively encounter EGFR inhibition during cetuximab treatment." (PMID 32481658, 2020). "Deregulated EGFR expression is present in various cancers including CRC; increased EGFR expression is present in 25–77% of CRC cancers." (PMID 33374459, 2020). "Mesenchymal-epithelial transition tyrosine kinase receptor (MET)/epidermal growth factor receptor (EGFR) TKIs were commonly used for cancer chemotherapy." (PMID 32050640, 2020). "There are developed targeted therapy by targeting cancer driver genes such as epidermal growth factor receptor (EGFR) and anaplastic lymphoma kinase (ALK)." (PMID 33238593, 2020). "In this study, we used different EGFR-targeting drugs which were already FDA-approved for treatment of different types of cancer as potential novel host-directed antiviral substances against poxvirus infections." (PMID 33198108, 2020).